LINC01546 (long independently transcribed non-coding RNA 1546)
Synonyms: VAL; formerly CXorf28
Gene: Long non-coding RNA gene on chromosome X (3,271,504 to 3,291,550, forward strand). Ensembl gene ENSG00000228459.
Diseases named in the same sentence as LINC01546 in open-access papers:
LINC01546 is named in the same sentence as 5 diseases in open-access papers, as found by Europe PMC text mining. Sharing a sentence is not in itself a finding about the gene and the disease.
LINC01546 shares sentences with these, for which no sentence is quoted: cancer (2 papers); lung adenocarcinoma (2); tumor (2); gastric cancer (1); lung carcinoma (1).